EZH2 (enhancer of zeste 2 polycomb repressive complex 2 subunit)
Diseases named in the same sentence as EZH2 in open-access papers (continued):
Sharing a sentence is not in itself a finding about the gene and the disease.
tumor (continued). "Research in the mechanism of miR-31 found that it could target genes such as ARID1A, SATB2, ARID1A, HuR, BAP1, EZH2, and RASA1, and it could further activate oncogenes and promote tumor cell proliferation, migration and invasive capability in vitro." (PMID 28404921, 2017). "EZH2 has been acknowledged as a histone methyltransferase catalytic subunit, which comprises part of a polycomb repressor complex (PRC2) and is reported to silence tumor suppressor genes when upregulated in cancers." (PMID 28416772, 2017). "Recently, we provided evidence that pharmacological EZH2 inhibition using UNC1999 exerts anti-MM effects by reducing the levels of H3K27me3 and de-repression of bivalent genes involved in tumor suppressor functions such as apoptosis and cellular differentiation." (PMID 28052011, 2017). "Enhancer of zeste homolog 2 (EZH2), a crucial component of polycomb repressive complex 2, is highly expressed in multiple cancer types, making it an attractive therapeutic target in tumor treatment." (PMID 28088786, 2017). "However, all samples from low to high-grade adenocarcinoma revealed strong expression of tumor form of MUC1, phopsho-p65 and EzH2." (PMID 29285251, 2017). "While short-term exposure to high concentrations of PEITC (6–12 μM for 48 h) was sufficient to reduce tumor cell expression of BMI-1, marked decreases in the expression of key PcG complex proteins SUZ12 and EZH2 were only observed after long-term treatment (2.5 μM PEITC for 6 weeks)." (PMID 28079155, 2017). "Furthermore, our data provided the first evidence that XIST functions as a molecular sponge for miR-101 and EZH2 and knockdown of XIST exerted tumor-suppressive functions in human ESCC by epigenetic regulation of EZH2 via reciprocal repression of miR-101." (PMID 29100288, 2017). "Consist with the results obtained from the in vitro study, immune-histochemical analyses demonstrated that the expression levels of EZH2, H3K27me3, MMP2, Vimentin, N-cadherin, ki-67 and Cyclin D1 were downregulated in tumor specimens from the GSK343-treated group." (PMID 29228694, 2017). "For instance, EZH2-positive IM tumor cells formed epiretinal membranes over EZH2-negative neural retina." (PMID 27842164, 2016). "As recently more and more research groups devote to explore molecule targeting inhibitors of histone methyltransferase, such as EZH2- H3K27 inhibitor EPZ – 6438 and DOT1L- H3K79 methylation inhibitors EPZ– 5676, it has become a promising target for anti-tumor therapy." (PMID 27144429, 2016). "EZH2 knockdown significantly reduced the CD133+/CD44+ subpopulation, suppressed mammosphere formation, and decreased the expression of self-renewal-related genes and strongly impaired tumor-initiating capacity in a re-implantation mouse model." (PMID 27172794, 2016). "Further investigation into the potential negative impact of CXCR4 activation on tumor progression is warranted in preclinical studies of EZH2-inhibition." (PMID 27528222, 2016). "Independent of tumor proliferation, the expression level of EZH2 was identified as a prognostic factor in MCL, using multivariate survival analysis." (PMID 27998273, 2016). "As a tumor promoter, MALAT-1 could be transcriptionally activated by c-Fos and could interact with Ezh2, silencing the tumor suppressor gene E-cadherin and upregulating β-catenin expression that induce tumor promotion in RCC." (PMID 27806310, 2016). "In addition, inhibition of EZH2 by ZLD1039 restored the expression of cell cycle inhibitors and tumor suppressors." (PMID 26868841, 2016). "We show here that the SAM-competitive EZH2 inhibitor UNC1999 exhibits low micromolar cytotoxicity in vitro on a diverse collection of BTIC lines, synergizes with Dexamethasone (DEX) and suppresses tumor growth in vivo in combination with DEX." (PMID 27449082, 2016).
tumor (continued). "Although miR-361 was reported to act as a tumor suppressor, its (most significant) overexpression in A549 cells did not change the expression level of EZH2 (NS, not statistically significant." (PMID 27049834, 2016). "Second, because EZH2 is specifically expressed in IM tumor cells, but not other nontumor cells, EZH2 represents an attractive avenue for targeted therapy for intraocular cancers." (PMID 27842164, 2016). "All round or spindle shaped tumor cells strongly expressed EZH2, in contrast to the cells in the fibrous septa and the vasculature of the tumors, which were EZH2-negative." (PMID 26848979, 2016). "HULC induced tumor proliferation, migration and cell cycle progression by modulating the expression of Cyclin A/D1/E, p-Rb, c-Myc, CDK2/4, and p16/p21/27, which are targets of Skp-1/2 and inhibitors of CDK2/4 and EZH2." (PMID 26894862, 2016). "EZH2, the catalytic component of polycomb repressive complex 2 (PRC2), is frequently overexpressed in human cancers and contributes to tumor initiation and progression, in part through transcriptional silencing of tumor suppressor genes." (PMID 26871474, 2016). "We then investigated whether NT1721 influenced the expression of tumor suppressor genes since several reports have shown links between the downregulation of DNMT1, BMI1 and EZH2 and increased expression of tumor suppressor genes." (PMID 27863389, 2016). "Regardless of the molecular mechanism involved, EZH2 overexpression leads to higher levels of the repressive H3K27me3 mark, responsible for the silencing of tumor suppressor genes in cancer cells." (PMID 27222667, 2016). "We believed that our findings provided the novel insight into the connection between SAPK/JNK signaling and expression of DNMT1 and EZH2 affected by PPI, and also highlighted the tumor suppressor role of SAPK/JNK that was involved in the anti-tumor effects of PPI." (PMID 27421653, 2016). "Moreover, by binding to enhancer of zeste homolog 2 (EZH2), LINC00152 promotes GC tumor cell cycle progression by silencing the expression of p15 and p21." (PMID 26799422, 2016). "It has been recognized that apoptosis and autophagy of tumor cells is crucial in tumorigenesis and progression of cancer, however, the exact role EZH2 plays in apoptosis and autophagy has not been fully elucidated in CRC." (PMID 27706111, 2016). "Inhibition of EZH2 and DNA methyltransferase 1 (DNMT1) resulted in increased expression of the Th1-type chemokines in cancer cells, leading to increased trafficking of effector T cells to the tumor site and decreased tumor volume." (PMID 27793053, 2016). "We found that the novel SAM-competitive EZH2 inhibitor UNC1999 exhibited low micromolar cytotoxicity in vitro on a diverse collection of BTIC lines, synergized with dexamethasone (DEX) and suppressed tumor growth in vivo in combination with DEX." (PMID 27449082, 2016). "Enhancer of Zeste Drosophila Homologue 2 (EZH2) is a key regulator of transcription as a member of polycomb repressive complex 2 (PRC2) which exerts repression of downstream genes and is correlated to invasiveness and progression of different tumours." (PMID 27471434, 2016). "Recent studies have demonstrated that inhibition of the interaction between EZH2 and other components of the PRC2 complex may be more a specific approach with efficacy against various neoplastic diseases and decreased toxicity." (PMID 27793053, 2016). "In contrast, all of the corresponding non-tumor gastric tissues showed negative or weakly positive immunostaining of EZH2 protein." (PMID 25890171, 2015). "Similarly to EZH2 knockdown, DZNep reverts epithelial-to-mesenchymal transition (EMT), and prevents tumor progression, making it a highly promising anti-tumour agent." (PMID 26268310, 2015). "MiR-101 is a microRNA involved in a negative feedback circuit with EZH2 in different normal and tumor tissues." (PMID 26251675, 2015).
tumor (continued). "Mammary-specific deletion of Ezh2 did not impair tumor development but in fact resulted in an increased penetrance of tumor formation." (PMID 26637281, 2015). "Inhibition of EZH2 in NHL cells induces Blimp-1, which impairs tumor growth." (PMID 26697022, 2015). "We also investigated whether EZH2 was important for TGF-β-mediated apoptosis and tumor formation in H345 cells." (PMID 27462425, 2015). "In hepatocellular, endometrial cancer and osteosarcoma, the tumor suppressive miR-101 targets EZH2, the catalytic subunit of the PRC2 (Polycomb Repressive Complex 2) complex, which is responsible of the H3K27me3-mediated silencing of tumor suppressor genes in cancer." (PMID 25968566, 2015). "Having validated our positive and negative controls for each subtype, we analyzed CBX2 and EZH2 protein levels in both tumor lines." (PMID 25859291, 2015). "Probing various publicly available datasets (GSE20347, GSE47404, GSE13937) to assess the expression of SOX4, EZH2 and HDAC3 in primary esophageal squamous and adenocarcinoma samples, we found SOX4 and EZH2 to be significantly upregulated in ESCC tumor samples (GSE20347), compared to normal tissues." (PMID 25644061, 2015). "To evaluate the effects of pharmacological inhibition of EZH2 in vivo, we next tested whether DZNep treatment blocked MPNST tumor initiation and growth in an MPNST724 xenograft mouse model." (PMID 25890085, 2015). "In support of our prediction, a more recent study has suggested that enhancer of zeste homologue 2 (EZH2), a member of the polycomb group of genes (PcG), is overexpressed in human cancer tissues and can directly induce VASH1 methylation and promote tumor angiogenesis." (PMID 25797264, 2015). "Data showed that DZNep decreased the EZH2 and KPNB1 protein levels of tumor samples." (PMID 25890085, 2015). "In the present work, we first analyzed EZH2 expression in a Chinese HNSCC cohort and HNSCC cohort form TCGA, and we further identify inhibition of EZH2 inducing HNSCC cell apoptosis in cell lines in vitro and in a Cal27 derived tumor model." (PMID 26378043, 2015). "This may lead to tumor progression and the metastasis of EAC and ESCC; SOX4, EZH2, HDAC3 and miR-31 emerge as potential therapeutic targets." (PMID 25644061, 2015). "Moreover, EZH2 is considered one of the most appealing epigenetic targets for therapy in human cancer but efficiency of how it regulates its target genes depends on a number of additional factors, which may differ from one tumor cell line to another, even of the same tissue." (PMID 26268310, 2015). "Borno and co-workers however, also identified a miRNA-dependent mechanism for EZH2 overexpression in TMPRSS2:ERG negative tumours." (PMID 25496077, 2014). "We also observed that transfection EZH2, MCL-1 and FOS siRNA significantly inhibited the ability of SPAC-1-L and HEC-50 cells to invade and to form spheres, mimicking the tumor suppressive effects upon miR-101 overexpression." (PMID 25153722, 2014). "We found that 14-3-3σ and EZH2 were highly expressed in HCC (71% and 90%), the expression of EZH2, but not 14-3-3σ, is associated with vascular invasion and tumor differentiation (p<0.01)." (PMID 25226601, 2014). "Sestrin 1 (SESN1), a putative tumor suppressor and mTOR signaling inhibitor, was identified as a gene synergistically up-regulated commonly in 3 of 4 EZH2 mutant cells with combination treatment, but not in EZH2 wild-type cells." (PMID 25493630, 2014). "Interestingly, similarly to EZH2 knockdown, DZNep reverts epithelial-to-mesenchymal transition (EMT), and prevents tumor progression, making it a highly promising antimetastatic agent." (PMID 24852755, 2014). "The expression level of EZH2 was negatively correlated with SPRY4-IT1 expression levels in NSCLC tissues, and increased EZH2 expression in NSCLC tissues significantly correlated with tumor size, advanced pathological stage, and lymph node metastasis." (PMID 24967960, 2014).
tumor (continued). "EZH2 expression in intraductal hyperplasia was positive both outside and within the ILC, but the EZH2 expression in non-proliferative glandular epithelium varied and was negative within the tumor or positive apart from the ILC." (PMID 24266940, 2013). "Furthermore, pharmacological inhibition of PRC2 components, including EZH2, reduces expression of CSC markers and decreases tumor formation and growth in multiple types of cancers." (PMID 24172544, 2013). "Indeed, PcG proteins EZH2, BMI1 and CBX7 have been shown to possess oncogenic or tumor suppressor functions in different tumors including GBMs." (PMID 24260522, 2013). "We observed that newly derived FC-IBC-02 suspension cell population formed tumor spheroids, a characteristic of CSC and expressed a higher level of EZH2 and generated larger tumor in size compared to initial adherent cell population when transplanted into the mammary fat pads of SCID mice." (PMID 24294976, 2013). "Disruption of EZH2 by DZNep induced apoptosis, inhibited cell invasion and enhanced chemotherapeutic sensitivity, but not normal and untransformed cells at tumor-inhibiting doses." (PMID 24345883, 2013). "EZH2 catalyzes the trimethylation of histone H3 on Lys 27 (H3K27) and is involved in gene repression and contribute to CaP tumorigenesis through silencing of tumor suppressor genes." (PMID 24202331, 2013). "Additionally, over expression of EZH2, the catalytic unit of PRC2, in lymph node metastasis strongly correlated with tumor cell proliferation in situ." (PMID 23251464, 2012). "Previously, it has been shown that EZH2 mediates transcriptional silencing of E-cadherin by trimethylation of H3K27 and that HDAC inhibitors could attenuate tumor invasion by blocking EZH2- mediated repression of E-cadherin." (PMID 23251464, 2012). "In the present study, we found that miR-98 and miR-214 expression were both inversely correlated with EZH2 protein expression in human ESCC, and that down-regulation of miR-98 and miR-214 expression was significantly correlated with pathological grading, tumor stage and lymph node metastasis." (PMID 22867052, 2012). "The treatment of PCa cells with CDF, a novel Curcumin-derived synthetic analogue previously showed anti-tumor activity in vivo, inhibited the productions of VEGF and IL-6, and down-regulated the expression of Nanog, Oct4, EZH2 mRNAs, as well as miR-21 under hypoxic condition." (PMID 22952749, 2012). "Several reports suggest that EZH2 directly interacts with DNA methyltransferases (DNMT1, DNMT3A, DNMT3B) and that EZH2 is necessary for the maintenance of DNA methylation and stable repression of specific genes, including many tumour suppressors." (PMID 22187039, 2012). "Similarly, WWP1, SDC1 (syndecan 1), EZH2, CCND1, ADAM9 and MEMO1 have oncogenic activities and are targeted by the potentially tumor suppressor miRNA miR-195, miR-10b, let-7c, miR-17 and miR-125b." (PMID 21375733, 2011). "Conversely, the EZH2-reactive CD4 T-cell clones were unable to recognize naturally processed epitopes derived from tumor cell lysates via DCs (data not shown)." (PMID 22053850, 2011). "Regarding the effects of EZH2 inhibition in vivo, we performed Ki67 staining on tumor slices of mice treated with or without the EZH2 inhibitor DZNep." (PMID 21297974, 2011). "In addition, we showed concomitant abnormal expression of miR-26a and EZH2, the former being highly down-regulated and the latter abnormally expressed in RMS tumor samples and cell lines compared to controls." (PMID 21943149, 2011). "It has been recently reported that miRNA-101 targets the enhancer of Zeste homolog 2 (EZH2); the low expression level in several tumor types could lead to up-regulation of EZH2 in aggressive tumors with an invasive phenotype." (PMID 20929526, 2010). "In overt tumours, faint staining of both proteins was observed, except for EZH2 expression in EC, which was totally absent (data not shown)." (PMID 20823885, 2010).
tumor (continued). "EZH2 was among the 169 up-regulated genes both in ERGhigh and ESE3low tumors genes while it was not increased in the other tumor subgroups." (PMID 20479932, 2010). "The differential association with survival suggests that EZH2 and BMI1 are not overexpressed in the same tumours." (PMID 19099573, 2008). "There is currently no commercially available antibody for EZH2, so we used RT–PCR to analyse EZH2 mRNA expression in tumour cell lines." (PMID 17024127, 2006). "The findings of this study indicate that EZH2 mRNA expression was upregulated in human HCC and may play an important role in tumour progression, especially by facilitating portal vein invasion." (PMID 15856046, 2005). "Other pathological variables, such as the tumour diameter, capsular formation and intrahepatic metastasis, did not significantly correlate with the EZH2 expression status in tumour tissue specimens." (PMID 15856046, 2005). "Notably, the role of EZH2 involves the epigenetic regulation of TFR2 expression, which further inhibits ferroptosis and enhances drug resistance, a process closely related to cell cycle regulation and tumor proliferation and metastasis." (PMID 40465746, 2025). "In addition, inhibition of enhancer of zeste homolog 2 (EZH2), a regulator of histone methylation, may also significantly enhance anti-tumor activity of CAR T cells." (PMID 41346587, 2025). "Specific to both intact and castrated treated groups, EZH2 inhibition alone did not provide anti-tumor efficacy, whereas response to PI3K/mTORC1 inhibition alone provided significant anti-tumor effect against intact tumors, but acquired resistance was noted in castrated conditions." (PMID 40832297, 2025). "Notably, we observed that 95.0% (n = 19/20) of PD-L1 expressing tumour cells were negative for EZH2, although this inverse relationship was not statistically significant (p > 0.05)." (PMID 40310411, 2025). "The findings revealed that tumour models generated from seeded HNSCC cells without EZH2 knockdown exhibited more abnormal cellular features and tissue structure including a disrupted basement membrane, enlarged cell nuclei, little cytoplasm, and spindled cellular morphology." (PMID 41614754, 2025). "Taken together, our data support a model in which EZH2 overexpression drives HB tumor progression through both canonical and noncanonical mechanisms, associated with dysregulated mitosis, altered PRC2 complex integrity, and potential epigenetic modulation of CDH1 signaling." (PMID 40766612, 2025). "However, the lack of tumor specificity in EZH2 inhibitors results in off-target adverse effects, thereby constraining their clinical utility." (PMID 40708008, 2025). "The exact reason why EZH2 mutations did not impact the PFS significantly is unknown, but the suggested reasoning is that activated AKT phosphorylates EZH2 leading to tumor growth." (PMID 39984775, 2025). "In addition, enhancer of zeste homolog 2 (EZH2) inhibitors are new drugs for the treatment of cancers lacking SMARCB1, and preclinical studies have shown that they have the potential to modulate tumor immunogenicity and antitumor immune responses." (PMID 40115023, 2025). "Targeted selective inhibition of EZH2 with tazemetostat upregulates the expression of HLA class I molecules in anti-PD-1-resistant HNSCC cell lines and mouse models and increases antigen-specific CD8+ T cell proliferation, IFN-gamma production, CXCL10 expression, and tumor cell cytotoxicity." (PMID 39941804, 2025). "Overall, consistent findings across multiple studies underscore the potential of EZH2 as a therapeutic target and prognostic biomarker in HCC while emphasizing the need for further research to clarify its mechanistic pathways and interactions within the tumor microenvironment." (PMID 41298718, 2025).